CD4 (CD4 molecule)
Diseases named in the same sentence as CD4 in open-access papers (continued):
Sharing a sentence is not in itself a finding about the gene and the disease.
tuberculosis (continued). "Although our own ongoing studies and limited reports indicate only a moderate role for IL-3 in murine models of tuberculosis and HSV, there are indications for other possible roles for IL-3–producing CD4+ T cells, including in contact hypersensitivity and antiparasite immunity." (PMID 31356170, 2019). "Based on the findings of this review, tuberculosis co-occurrence is a frequent problem in people with histoplasmosis and advanced HIV; most of the reports came from the Latin American region and involved very ill patients (median CD4 T cell: 30 cells/mm3)." (PMID 31404979, 2019). "Although T-helper type 1 CD4+ cells (Th1) are required for control of mycobacterial infections, the enhanced CD4 activity in the absence of PD-1 surveillance exacerbates tuberculosis in mouse models." (PMID 31484550, 2019). "We addressed the role of CD4+Foxp3+ cells in tuberculosis pathogenesis, because this aspect has not been addressed during chronic infection." (PMID 30584243, 2018). "HIV is a potent risk factor for tuberculosis and complicates every aspect of tuberculosis care from prevention to diagnosis and treatment, whereas tuberculosis increases progression of HIV and contributes to slower CD4 recovery and faster virological failure on ART." (PMID 29698255, 2018). "Our findings are translationally relevant, as CD4+Foxp3+ cells or CCR4 could be a target for immunotherapy, considering the heterogeneity of tuberculosis in immunocompetent adults." (PMID 30584243, 2018). "Polyfunctional CD4+ T cells are those that simultaneously perform at least 2 functions and generally present a protective correlate against different chronic infections such as HIV infection, hepatitis C, tuberculosis and leishmaniasis." (PMID 29601585, 2018). "Physicians determined clinical eligibility of Same‐Day ART based on signs/symptoms and only results of CD4 and chest x‐ray to rule out tuberculosis, cryptococcal meningitis, and serious illnesses." (PMID 30051631, 2018). "However, little is known about the spectratyping characteristics of the CD4+ T-cell receptor (TCR) α- and β-chains CDR3 region in tuberculosis (TB) patients." (PMID 29967390, 2018). "Whilst other pathways may be operative, we provide unequivocal data to show that circulating HLA-DR+CD4+ effector memory T cells resistant to CCR5 and PD-L1 mediated suppression compromise regulatory T cell function in tuberculosis." (PMID 30231065, 2018). "Very recently, we have identified in the peripheral blood of patients with tuberculosis a novel human effector/memory CD4+ T cell subset with a non-classical, naive-like T cell phenotype." (PMID 30559746, 2018). "Twenty-seven HIV-infected control patients with CD4 cell counts <350/μL and negative results of screening for tuberculosis were included." (PMID 28363198, 2017). "By reframing the HIV disease variables in terms of systemic immune activation, which predicts HIV disease progression better than CD4+ T cell counts or HIV viral loads, we provide a novel paradigm for understanding the sources of pharmacokinetic variability among HIV/tuberculosis patients." (PMID 29095954, 2017). "We did not detect differences in the PPD response of CD4+ T cells between tuberculosis patients and healthy contacts in the present study." (PMID 28582466, 2017). "Male gender contributed the most to IHM (PAF=0.22), followed by unknown CD4 count (PAF=0.14), tuberculosis (PAF=0.12), renal failure (PAF=0.06) and CD4 count <350 cells/mm3 (PAF=0.01)." (PMID 28533849, 2017). "Previous studies suggest that CD4+ and CD8+ T-cell subsets and CD4:CD8 ratio play a central role in the induction of efficient immune responses against different diseases such as human immunodeficiency virus (HIV), tuberculosis, and cancer." (PMID 28575063, 2017).
tuberculosis (continued). "The adjusted tuberculosis incidence rate was 1.42 (95% CI 0.55–3.20) per 100 PY in women, aged 16–30 years, without prior tuberculosis history, with CD4 ≥500 cells/mm3 and haemoglobin ≥11 g/dl, followed in Burkina-Faso." (PMID 28953320, 2017). "Multivariable logistic regression adjusted for age at ART initiation, gender, pre-ART CD4 count, months on ART, and tuberculosis history indicated higher odds of retention in adolescents and young adults attending adolescent compared to standard clinic (AOR = 8.5; 95% CI 2.3–32.4; p = 0.002)." (PMID 29287088, 2017). "Genus Streptococcus, Veillonella and Escherichia showed no clear correlation with the CD4+ cells in the tuberculosis patients." (PMID 29204120, 2017). "Package of HIV care services in Georgia includes immediate ART regardless of CD4 cell count, treatment of co-infections such as hepatitis C and tuberculosis, as well as methadone substitution therapy for active drug users." (PMID 29084276, 2017). "Exposure of whole blood to mycobacterial lipoarabinomannan in vitro increased CCR5 expression on blood CD4 T cells, suggesting the increased levels of CCR5 expression in tuberculosis patients was mediated, at least in part, by cell wall components of Mycobacterium tuberculosis." (PMID 26762145, 2016). "Nonetheless, similarly to data already published, we demonstrated that for patients not using cART, higher nadir CD4+ T lymphocyte counts significantly reduced the incidence of tuberculosis." (PMID 27001753, 2016). "Some of these infections are not related exclusively to the reduction in the CD4 Tcells, as in the cases of tuberculosis and candidiasis." (PMID 27384466, 2016). "At the local infection site, the expressions of PD-1 and its ligands in pleural fluid of tuberculosis pleurisy were similar to those in peripheral blood, whereas the IFN-γ-producing CD4+ T cells at the local infection site increased significantly compared to that in peripheral blood." (PMID 27924827, 2016). "The Temprano randomized trial was conducted in Abidjan to assess the effectiveness of early ART and Isoniazid (INH) prophylaxis for tuberculosis in HIV-infected persons with high CD4 counts below 800 cells/mm3 without any indication for starting ART." (PMID 26925155, 2016). "Given the low median CD4 count at admission, it is not surprising that tuberculosis and other similar infections were the leading reason for admission and death of HIV-positive patients causing one fourth of all HIV-related deaths." (PMID 26885977, 2016). "One study revealed that a predominant Th1 immune response had been observed in non-cavitary tuberculosis patients while cavitary-involved segments of the lungs accumulated Th2 CD4+ T cell subsets." (PMID 26018190, 2015). "First, people with a history of IDU should be actively tested for HIV, and HIV treatment should be started according to WHO guidelines, especially because ART has been shown to protect against development of tuberculosis, irrespective of CD4 cell count." (PMID 25690530, 2015). "Regarding tuberculosis, since the majority of cases occurred in patients with CD4 count < 200 cells/mm3, it appears to be a marker of low CD4+ cells count nadir, rather than an independent factor for inadequate immune restoration." (PMID 26355305, 2015). "Adults (aged ≥18 years) with a CD4 count of 150 cells/μL or less, who have not received any tuberculosis treatment in the last three months, or ART in the last six months, are eligible." (PMID 25872501, 2015). "All the 60 antiretroviral drug naïve individuals had a CD4 count ≥350 cells/mm3 with a median CD4 count of 436 (range 360–780) and tested negative for tuberculosis." (PMID 25962059, 2015). "To study the distribution of Tfh cells in TB infections, we examined Mtb antigen-specific induction Tfh cells subsets (defined as CD4+ CXCR5+ PD-1+ ICOS− or CD4+ CXCR5+ PD-1− ICOS+ or CD4+ CXCR5+ PD-1+ ICOS+) in PTB and LTB individuals in an area highly endemic for tuberculosis." (PMID 25343703, 2014).
tuberculosis (continued). "As per operational research procedures, the ECO was expected to conduct regular ward rounds in the Tuberculosis, HIV and Kaposi Sarcoma Units to recruit potential study participants among the HIV-infected inpatients having eye complaints or whose latest CD4 count was below 100 cells/μl." (PMID 25767656, 2014). "For certain patient groups, ART is recommended irrespective of CD4 count (PLHIV with active tuberculosis, hepatitis B virus infection, pregnant and breast feeding women, children aged under five years and those living in a sero-discordant relationship)." (PMID 25192338, 2014). "Conversely, 25(OH)D levels were lower in patients with active tuberculosis compared with those without (34 nmol/L vs 39 nmol/L; P = .029), and this difference remained significant after adjusting for CM case status and CD4 count (P = .04)." (PMID 24825871, 2014). "Marital relationship, the absence of tuberculosis, the absence of wasting, CD4 count ≥ 350 cells /mm3 and use of HAART positively impacted QOL of our patients." (PMID 25426192, 2014). "Marital relationship, absence of tuberculosis, CD4 count ≥ 350 cells /mm3 and use of ART positively impacted QOL of our patients." (PMID 25426192, 2014). "Apart from mortality, clinical implications of poorer CD4 cell recovery amongst older adults were not measured, such as incident tuberculosis or AIDS-defining illnesses, as these data were not collected." (PMID 24949879, 2014). "Most identified that CD4 counts were used to assess antiretroviral (ARV) therapy eligibility among HIV patients (38/40; 95%) and knew that isoniazid preventive therapy was used to prevent tuberculosis (36/40; 90%)." (PMID 23866794, 2013). "However, we found that patients with CD4 counts <150 cells/μL had a high risk of death and loss to followup, so these patients may benefit from “fast tracking” interventions to rule out tuberculosis and other opportunistic infections and to provide intensive adherence counselling." (PMID 24288689, 2013). "In a study of tuberculosis contacts there was no percentage difference in CD4+ or CD8+ memory phenotype at baseline in progressors and nonprogressors arguing against a causal role." (PMID 23966657, 2013). "Two recent studies from a prospective HIV-tuberculosis cohort treated for tuberculosis, conducted in Uganda showed that TB therapy strongly reduced the expression of CD38 and/or HLA-DR expression on CD8 T while for CD4 cells the reduction in the expression of these markers was less pronounced." (PMID 23840403, 2013). "Studies suggest that the induction of regulatory T cell subpopulations (CD4+/CD25+/Foxp3+) may impair activation of the specific T cell repertoire (both CD4+ and CD8+) in active tuberculosis." (PMID 23824716, 2013). "Our functional data therefore partially corroborates and extends earlier observations that measurement of the frequency of M. tuberculosis-specific CD4+ effector-like cells secreting IFN-γ and/or TNF-α can distinguish active tuberculosis from latent tuberculosis infection." (PMID 23966657, 2013). "We have determined CD4 cell levels longitudinally during anti-tuberculosis treatment (ATT) in patients, with and without HIV co-infection, and their associations with clinical variables." (PMID 24358268, 2013). "We compared the expression of 29 miRNAs in CD4+ T cells from peripheral blood of tuberculosis patients, LTBI, and non-infected control donors (PPDneg)." (PMID 23613882, 2013). "In this study, TNF-α-single-positive Mycobacterium tuberculosis-specific CD4+ T cells were preferentially detected in active tuberculosis disease rather than in latent infection." (PMID 23638039, 2013). "The findings were similar (but achieved statistical significance) in the multivariable model: patients on ART when tuberculosis was diagnosed had a higher rate of death than those diagnosed with tuberculosis prior to ART initiation, after adjusting for CD4+ lymphocyte count and HIV-1 RNA." (PMID 24066096, 2013).
tuberculosis (continued). "Factors associated with a higher probability of death were diagnosis of tuberculosis within three months of ART eligibility, being homeless, lower CD4 count, shorter duration of pre-ART care, belonging to a disadvantaged community, illiteracy, and age >45 years." (PMID 24288689, 2013). "The sole exception, the BCG vaccine against tuberculosis, appears to protect primarily by induction of CD4+ rather than CD8+ T cells." (PMID 24284865, 2013). "For this purpose we initially compared expression of 29 pre-selected immune-related miRNAs in CD4+ T cells of tuberculosis patients, healthy LTBI, and non-M." (PMID 23613882, 2013). "In 2009, WHO recommended antiretroviral therapy for all adults with CD4 counts less than 350 cells/μl and for all tuberculosis patients irrespective of CD4 count." (PMID 22911011, 2012). "That is, study participants starting ART when their CD4 count was below 200 cells/μl were about one-sixth as likely to develop tuberculosis as participants not receiving ART." (PMID 22911011, 2012). "In other disease models, extensive work has focused on the role of multifunctional T cells, both CD4+ and CD8+, and protection from disease or lessening of disease severity in a variety of infections: HIV, tuberculosis, malaria, leishmaniasis, influenza, and vaccinia." (PMID 22816004, 2012). "If patients could be diagnosed of HIV with higher CD4+ lymphocyte count, ART could be started before the appearance of tuberculosis, averting the transmission of tuberculosis to others as well." (PMID 23316226, 2012). "The severity of M. tuberculosis infection may be detected by measuring CD4+ and CD8+ T cells, as their numbers markedly decrease in patients with severe tuberculosis, which can be a sign of suppressed cellular immunity in these patients." (PMID 22400039, 2012). "WHO recommends ART for all HIV-positive adults with a CD4 count of less than 350 cells/μl of blood and for all HIVpositive, tuberculosis-positive individuals irrespective of their CD4 count." (PMID 22911011, 2012). "We also found that administration of antigen 85B peptide 25, which isrecognized by a high proportion of M. tuberculosis-specificCD4+ T cells, reduced the bacterial burden in the lungs,indicating that stimulation of existing antigen-specific CD4+ Tcells may be a promising approach to therapy of TB." (PMID 21637811, 2011). "Higher odds of dual method use were observed among women with one or more living children, those with CD4+ cell counts ≥351 cells/uL, and those who did not report a history of tuberculosis." (PMID 22007138, 2011). "Risk factors for TB-IRIS include low baseline CD4 count, high baseline viral load, short duration between TB and ART initiation and disseminated tuberculosis, making difficult to determine the optimal time to initiate ART in severely immune-suppressed TB patients." (PMID 22114934, 2011). "In line with these new recommendations South Africa recently changed the eligibility criteria for ART to include all pregnant women and patients diagnosed with tuberculosis who are HIV infected and have a CD4 count below 350 cells/μL compared to only patients with a CD4 count below 200 cells/μL." (PMID 21379378, 2011). "Thus, adults with a CD4 <50, Stage 4 HIV, previous ARV treatment, who were on tuberculosis (TB) or other chronic medication, were bedbound, or who were pregnant were identified as potentially complicated cases that needed to be initiated onto ART by a doctor." (PMID 21810242, 2011). "Molly Franke, Megan Murray, and colleagues report that early cART reducesmortality among HIV-infected adults with tuberculosis and improves retention incare, regardless of CD4 count." (PMID 21559327, 2011). "Since all the HIV-positive (and negative) patients with tuberculosis were unresponsive to Ag85, their inability to react with this antigen was clearly not related to the CD4+ T cell count." (PMID 20936150, 2011).
tuberculosis (continued). "Patients co-infected with tuberculosis tended to start cART at higher CD4 cell counts than patients without tuberculosis (142 versus 117 cells/μl, p = 0.060)." (PMID 21504595, 2011). "Consistent with our previous finding in patients with tuberculosis, we found IL-6R expression on CD4+ T cells, but not plasma IL-6, correlated with the Th17 response in HBV infected individuals." (PMID 21639870, 2011). "For example, the relative frequencies of CD4+ T helper cells and CD8+ T cytotoxic cells is known to become altered by many microbes, for example CD4+ T lymphocytopenia has been documented in some cases of tuberculosis." (PMID 20626864, 2010). "Although the importance of CD4 T cells in nonhuman primate models of tuberculosis has been reported, data are currently lacking on the role of CD8 T cells." (PMID 19381260, 2009). "Patients who were HIV positive tuberculosis negative had higher CD4+ T cells count than the HIV tuberculosis coinfected patients." (PMID 18826574, 2008). "We evaluated five of the outcome measures that were identified in that previous work (HAART prescription, PCP prophylaxis, tuberculosis screening, cervical cancer screening, and influenza vaccination) as well as MAC prophylaxis and measures of frequency of CD4 count and HIV viral load tests." (PMID 18806878, 2008). "Nearly 80% of residents (n = 105) correctly would not delay initiation of HAART until active tuberculosis had been completely treated in HIV-infected patients with CD4 cell counts below 100 cells/mm3 (Question #20)." (PMID 17678548, 2007). "No-ART patients with CD4 < 50 cells/μl had 3.4 clinic visits, 0.7 inpatient days, and 0.1 tuberculosis cases per patient-quarter." (PMID 17147833, 2006). "In the ART intervention, health service utilisation was highest for patients with CD4 < 50 cells/μl during the initial stages on treatment, with 10.5 clinic visits including pre-ART work-up, 1.1 days in hospital and 0.08 tuberculosis cases in the first 3 months." (PMID 17147833, 2006). "Notably, tuberculosis patient serum samples affected exclusively phytohemagglutinin stimulated T-cell responses and particularly activation marker as well as CD40L/IL-2 positive CD4+ T-cell subsets were decreased as compared to serum from healthy contacts." (PMID 41795482, 2026). "For instance, age, Sex, Poverty, Occupation, CD4, extra-tuberculosis, Anaemia, WHO stage and Functional Status were commonly reported predictors of mortality among TB-HIV co-infected individuals." (PMID 41296749, 2025). "Following standard anti-TB therapy, we evaluated the level of dual (IFN-γ + TNF-α+) cytokine-producing CD4 + T cell activation and proliferation markers from M. tuberculosis-specific, smear-negative PTB patients." (PMID 40901996, 2025). "In addition, we did not include certain variables because of the degree of missingness such as CD4 cell count, HIV viral load (both of which were dichotomized to included or missing), pregnancy status, comorbidities including tuberculosis, and other potential confounders." (PMID 40112252, 2025). "This hypothesis is supported by the lower CD4 cell counts observed in our study among participants on BIC/FTC/TAF, as well as the fact that the differences in IR were more pronounced when participants with tuberculosis were excluded." (PMID 40152537, 2025). "Although a history of tuberculosis and CD4+ count <100 cells/mL are among the risk factors for IA in AHD, depletion of CD4+T cells does not appear to play a central role in the pathogenesis of aspergillosis, but rather the depletion of neutrophils and macrophages." (PMID 40172196, 2025). "In contrast, HIV viral load, gender, ART adherence, and co-infections (HBV, HCV, and tuberculosis) were not statistically significant predictors (p > 0.15), suggesting that their impact on candidiasis is mediated primarily through CD4+ depletion rather than direct effects." (PMID 40428813, 2025).